RNU6-893P (RNA, U6 small nuclear 893, pseudogene)
Gene: Small nuclear RNA gene on chromosome 11 (112,032,499 to 112,032,598, reverse strand). Ensembl gene ENSG00000238444.
Homologues: Orthologues: macaque U6 (90% identical). Paralogues in human: RNU6-11P (93% identical), RNU6-37P (93% identical), RNU6-33P (92% identical), RNU6-43P (92% identical), RNU6-1 (91% identical), RNU6-116P (91% identical), RNU6-15P (91% identical), RNU6-2 (91% identical), RNU6-25P (91% identical), RNU6-3P (91% identical), RNU6-41P (91% identical), RNU6-4P (91% identical), and 1287 more.